FTO (FTO alpha-ketoglutarate dependent dioxygenase)
Diseases named in the same sentence as FTO in open-access papers (continued):
Sharing a sentence is not in itself a finding about the gene and the disease.
breast cancer (continued). "In our analysis, FTO expression was significantly higher in the breast cancer cell lines MDA-MB-231 and BT-549 compared to the non-tumorigenic MCF-10A cell line." (PMID 41281757, 2025). "We examined the effect of FTO knockdown on the proliferation and migration of the breast cancer cell lines MDA‐MB‐231 (triple‐negative breast cancer) and MCF‐7 (luminal A type metastatic adenocarcinoma) using short hairpin lentiviral vectors (shFTO)." (PMID 40022434, 2025). "Collectively, these findings highlight dual inhibition of FTO and BTK as a promising therapeutic strategy for maintaining low c-Myc and E2F1 expression levels, thereby improving survival outcomes and guiding future clinical management of breast cancer." (PMID 41281757, 2025). "Notably, the m6A demethylases FTO and ALKBH5 have been reported to be functionally essential in a variety of tumors such as AML and breast cancer." (PMID 40435251, 2025). "Here we present data showing that FTO expression stimulates the proliferation and migration of MDA‐MB‐231 (triple‐negative breast cancer) and MCF‐7 (luminal A type metastatic adenocarcinoma) breast cancer cells in cell culture." (PMID 40022434, 2025). "Given the upregulation of FTO in breast cancer and its potential role in cancer initiation and progression, we examined the effects of FB23, a potent FTO inhibitor that exhibits 140-fold greater efficacy than MA in inhibiting FTO-mediated demethylation 12, on breast cancer cells." (PMID 41281757, 2025). "After identifying that the combination of an FTO inhibitor and ibrutinib can function as an agent against breast cancer cells, we next used BALB/c-nu mice to investigate the specific effects of this combination on breast cancer progression in vivo." (PMID 41281757, 2025). "We elucidated that GAS5 suppressed breast cancer growth via IGF2BP2/QKI, and this inhibitory effect could be attenuated by FTO." (PMID 38782769, 2024). "Furthermore, biological function experiments showed that GAS5 suppressed breast cancer growth via IGF2BP2/QKI, and this inhibitory effect was modulated by FTO both in vitro and in vivo, thus representing a promising strategy for the treatment of breast cancer." (PMID 38782769, 2024). "FTO promotes the stability and expression of ZEB1 transcripts by decreasing m6A RNA methylation, leading to chemoresistance and epithelial-mesenchymal transition (EMT) of breast cancer cells." (PMID 38782769, 2024). "Furthermore, FTO inhibitors have been shown to reduce PI3K and Akt levels in breast cancer cells, leading to decreased activities of pyruvate kinase and hexokinase, thereby inhibiting glycolysis." (PMID 39192357, 2024). "The knockdown of FTO or STAT3 decreased doxorubicin resistance, which could be a potential strategy in the treatment of breast cancer." (PMID 37264402, 2023). "Strikingly, WTAP and the eraser FTO were downregulated in breast cancer cell lines compared to normal epithelial cells, whilst no changes were observed for ALKBH5." (PMID 36725888, 2023). "In addition, we did not investigate the prognostic value of FTO,PIK3CB on breast cancer, so we hope to explore the prognostic significance of FTO,PIK3CB on breast cancer in subsequent experiments." (PMID 37861518, 2023). "The FTO/miR-181b-3p/ARL5B axis modulates the migration and invasion of breast cancer cells." (PMID 36553003, 2022). "As the data shown, the OS of breast cancer patient was significant difference when gene expression was changed in ALKBH3 (p=0.00063), ALKBH4 (p=0.013), ALKBH7 (p=0.0025), ALKBH8 (p=0.00013) and FTO (p=0.045)." (PMID 35980268, 2022). "Several potent FTO inhibitors have been demonstrated to suppress the proliferation of cancer cells, such as R-2HG, FB23-2, CS1, CS2, and SsD in leukemia cells; MA2 in GSCs; and MO-I-500 in breast cancer cells." (PMID 35628623, 2022). "Past studies have demonstrated that the expression level of FTO in HER2-positive breast cancer tissues is higher than that in non-tumor tissues." (PMID 36561529, 2022).
breast cancer (continued). "FTO also provided deep insights in AML, breast cancer, and melanoma." (PMID 34149432, 2021). "Furthermore, the deceased patients had relatively reduced expression of FTO, METTL3, and METTL14 in tumor tissues, and increased levels of YTHDF1 and YTHDF3 than the alive patients who were diagnosed with breast cancer at the same period." (PMID 34804948, 2021). "Demethylases (FTO and ALKBH5) and methyltransferases (such as Metl3 and Metl14) have been reported to regulate the progression of several types of cancers, including liver, lung, and breast cancers 49-52." (PMID 34512165, 2021). "Studies have proved that FTO is not only limited to playing a major role in obesity-related diseases, but is also involved in the occurrence, development, and prognosis of a variety of cancers, including AML, glioblastoma, and breast cancer." (PMID 34149432, 2021). "Several members of m6A writer complexes and readers exhibited 1% mutation frequency, while main methyltransferases (METTL3, METTL14) and demethylases (FTO, ALKHB5) did not mutate in breast cancer samples." (PMID 34804948, 2021). "To investigate whether BNIP3 mediated FTO-dependent tumor growth and progression, we generated two distinct shRNAs targeting BNIP3 (shBNIP3–1 and shBNIP3–2) in FTO stable knockdown breast cancer cells." (PMID 30922314, 2019). "In addition, targeting the FTO and PDK1/AKT signaling axes with FB23 and BX-912 suppresses breast carcinoma progression, augments cytotoxic T-lymphocyte functionality, and synergistically enhances the therapeutic efficacy of the anti-PD-1/PD-L1 immunotherapy atezolizumab in preclinical models." (PMID 40986143, 2025). "Moreover, there was a negative correlation between the expression of GAS5 and FTO in breast cancer tissues and cells." (PMID 38782769, 2024). "In conclusion, GAS5 represses the growth of breast cancer through regulating the IGF2BP2/QKI pathway, and this inhibitory effect is modulated by FTO-mediated m6A modification, suggesting that the FTO/GAS5/IGF2BP2/QKI pathway may be a potential target for breast cancer treatment." (PMID 38782769, 2024). "This study not only further confirmed suppression of the immune evasion of AML through the FTO/m6A/LILRB4 axis in vitro and in vivo but also identified that these inhibitors possess therapeutic potential in treating solid tumors, including glioblastoma, breast cancer, and pancreatic cancer." (PMID 34381710, 2021). "FTO m6A-mediated demethylation of 3'- untranslated region BNIP3 transcript, which is a proapoptotic protein belonging to the Bcl-2 tumor suppressor family, promoting its degradation via YTHDF2 independent pathways and specific upregulation of BNIP3 retards breast cancer proliferation and metastasis." (PMID 33511112, 2020). "To investigate the molecular mechanism of FTO and identify its downstream targets in breast cancer, we performed transcriptome sequencing to examine the expression changes in our stable FTO-knockdown MDA-MB-231 cells and MCF-7 cells treated with DMOG, a FTO inhibitor (GSE3188)." (PMID 30922314, 2019). "In addition, the “writers” METTL3 and METTL14 were more predisposed to mutation or CNV than the other genes in ccRCC, while alterations of the “erasers” FTO and ALKBH5 were proved to be more important in breast cancer, glioblastoma and hematological malignancies." (PMID 30877265, 2019). "In other words, elevated YTHDF2 expression in FTO silencing breast cancer cells could not inverse the increasing of BNIP3 mRNA expression, indicating the presence of alternative mechanism to stabilize m6A-modified BNIP3 mRNA." (PMID 30922314, 2019). "In summary, we found that the FTO rs7185735 and MC4R rs476828 variants did not influence weight loss or improvement of metabolic parameters within the Mediterranean diet intervention in overweight or obese postmenopausal women with breast cancer receiving adjuvant hormone therapy." (PMID 35845810, 2022).
breast cancer (continued). "Further studies aimed at exploring the potential mechanisms that could help rare progenitor-like breast cancer cells survive metabolic challenges, indicated the involvement of several regulators of energy balance such as ARID5B, IRX5, and CUX1 P200 repressor besides FTO and IRX3." (PMID 27390851, 2016). "Mechanistically, FTO downregulates BNIP3 through demethylating m6A in the 3′ UTR of BINP3 mRNA and inhibits the apoptosis induced by it, thus promoting the proliferation of breast cancer cells, and this process is independent of YTHDF2." (PMID 40332101, 2025). "To study whether m6A modification of the CEBPB mRNA contributes to its translational regulation, we applied FTO knockdown (shFTO) in triple‐negative MDA‐MB‐231 and luminal A‐type MCF‐7 breast cancer cell lines, and mouse embryonic fibroblasts (MEFs)." (PMID 40022434, 2025). "Tan reported that FTO was highly expressed in hormone receptor (HR)-negative and HER2-positive BC patients, based on the immunohistochemical staining of specimens from 79 infiltrating ductal breast cancer (IDBC) patients." (PMID 33505967, 2020).
leukemia (159 papers, 2018 to 2026). A malignant (clonal) hematologic disorder, involving hematopoietic stem cells and characterized by the presence of primitive or atypical myeloid or lymphoid cells in the bone marrow and the blood. "In mice, FTO-KO in NK cells prevented melanoma metastasis in vivo, while in humans, FTO-deficient NK cells enhanced antitumor activity against leukemia." (PMID 40389988, 2025). "Its dysregulation via altered METTL3 or FTO expression is linked to glioblastoma, leukemia, and metabolic diseases." (PMID 40870000, 2025). "A previous study found that TKI resistance in leukemia was associated with reduced m6A due to FTO overexpression." (PMID 37264402, 2023). "First, fat mass and obesity associated protein (FTO) was found to promote leukemia initiation and progression, and is considered to have carcinogenic activity." (PMID 35720276, 2022). "A recent report on targeting aberrant mRNA modification in leukemia has highlighted another potential therapeutic approach to suppress fat mass and obesity-associated protein (FTO), an RNA N6-methyladenosine (m6A) demethylase." (PMID 34235155, 2021). "IDH mutation can inhibit the activity of m6A ‘eraser’ FTO in leukemia and glioma cells by producing R-2-hydroxyglutarate." (PMID 34246306, 2021). "In vivo studies have shown that FTO knockout in mouse NK cells prevents melanoma metastasis, whereas in vitro experiments have indicated that FTO-deficient human NK cells exhibit an enhanced anti-tumor response to leukemia, thereby providing a promising strategy for allogeneic NK cell therapy." (PMID 39759516, 2024). "The inactivation of FTO in leukemia causes the drug-resistant cells to become sensitive to tyrosine kinase inhibitors, suggesting that the FTO–m6A axis may serve as a new therapeutic target for human cancers." (PMID 35721711, 2022). "In FTO high cancer cells, including leukemia and glioma, R-2HG inhibited cancer cell proliferation/survival and promoted cell cycle arrest and apoptosis, while reversing drug resistance by targeting the FTO/m6A/MYC/CEBPA signaling pathway." (PMID 41362736, 2026). "High FTO expression inhibits apoptosis and promotes leukemia cell survival by affecting the PDGFRB/ERK signaling axis." (PMID 39802639, 2025). "FTO overexpression in leukemia can also generate a resistant phenotype against EGFR TKIs, and its downregulation resensitizes melanoma cells to interferon gamma (IFN-γ) and anti-programmed cell death protein 1 (PD1)." (PMID 40722726, 2025). "Leukemia cells appear to hijack FTO demethylation to elevate ribosome biogenesis, the disruption of which impairs the whole cell translation, particularly the translation of DNA replication–related genes, ultimately inhibiting AML progression." (PMID 40815637, 2025). "Mechanistically, R-2HG targets the FTO/m6A/MYC/CEBPA signaling pathway to inhibit the malignancy of leukemia cells with high FTO expression." (PMID 40823087, 2025). "FTO is also associated with many other cancers, such as gastric cancer, advanced non-small cell lung cancer (NSCLC), leukemia, and hepatocellular carcinoma." (PMID 40722726, 2025). "Some more recent published studies have also reported that FTO depletion leads to impaired growth in various leukemia cell lines and in certain hematologic cell types in mice." (PMID 41279954, 2025). "By disrupting this pathway, R-2HG effectively reduces the oncogenic potential of FTO-overexpressing leukemia cells, making it a promising therapeutic agent for leukemia treatment." (PMID 40823087, 2025). "The FTO/PFKP/LDHB axis has been shown to be involved in glycolysis in leukemia via m6A modification." (PMID 41373022, 2025). "FTO protein expression is unexpectedly upregulated by CS1 or FB23-2 treatment in multiple leukemia cell lines." (PMID 42004278, 2025). "FTO inhibition rendered leukemia cells more sensitive to T cell cytotoxicity and helped overcome immune evasion induced by low methylation agents." (PMID 39192357, 2024).
leukemia (continued). "Mechanistically, R-2HG directly targets the m6A demethylase FTO and inhibits its catalytic activity, thereby increasing m6A-modified RNA levels in R-2HG-sensitive leukemia cells." (PMID 39473440, 2024). "For AML cells, FTO promotes the cell cycle, inhibits apoptosis, and enhances autophagic activity, thereby promoting the survival of leukemia cells." (PMID 38711100, 2024). "Knockdown of FTO reduced the growth of leukemia stem cells and prevented leukemia cells from escaping the immune system." (PMID 39397802, 2024). "GNPIPP12MA targets the FTO/m6A pathway, synergistically enhancing anti-leukemia effects by depleting GSH." (PMID 39192357, 2024). "R-2-Hydroxyglutarate (R-2HG) attenuates aerobic glycolysis in leukemia by targeting the FTO/m6A/PFKP/LDHB axis, thereby modulating disease progression." (PMID 39295872, 2024). "Mechanistic studies revealed that FTO inhibition mediated by compound 40 and 41 can sensitize leukaemia cells to T cell cytotoxicity and overcome hypomethylation induced immune evasion." (PMID 38711100, 2024). "Both of these compounds show high efficacy for FTO inhibition as well as potent antitumor effects via suppression of self‐renewal capability in leukemia stem/initiating cells thereby overcoming immune evasion." (PMID 39661414, 2024). "The presence of other markers, such as NPM1 mutation type A, would induce FTO expression, resulting in TP53INP2 upregulation which promotes autophagy and leukaemia cell survival." (PMID 38545841, 2024). "To identify the general transcriptional regulators of FTO in different tissues, we used bioinformatics analysis of three other leukemia-related databases, GSE222811, GSE217109 and GSSE200446, to observe the expression of five enzymes associated with m6A." (PMID 39363112, 2024). "Mechanistically, FTO serves as a new lncRNA regulator through FTO-dependent m6A hypomethylation in leukemia resistant cells." (PMID 39764125, 2024). "Despite progress, the clinical potential of small-molecule FTO inhibitors is limited by moderate activity, toxicity, and low specificity for leukemia stem cells (LSCs)." (PMID 39192357, 2024). "In leukemia, FTO inhibitors block the FTO/m6A/MYC/CEBPA signaling axis, inhibiting the autologous renewal of tumor stem cells and the expression of the immune checkpoint LILRB4 and immune evasion, thereby enhancing the cytotoxicity of T cells." (PMID 38117350, 2023). "Rhein is the first natural FTO inhibitor which competitively binds to the catalytic domain of FTO and displays therapeutic efficacy in leukemia mice." (PMID 36810281, 2023). "FTO inhibitor-loaded glutathione-bioimprinted nanocomposites (GNPIPP12MA) are engineered to target the FTO/m6A pathway with glutathione depletion for synergistically improving anti-leukemia treatment efficiency." (PMID 36810108, 2023). "Genetic depletion and pharmacological inhibition of FTO not only dramatically attenuated self-renewal of leukaemia stem cells, but also reprogrammed immune response by suppressing LILRB4 expression." (PMID 37875589, 2023). "FTO is overexpressed in leukemia stem cells (LSCs), allowing the stable expression of many oncogenes." (PMID 37007161, 2023). "R-2HG is an FTO targeted inhibitor that has been shown to significantly increase m6A levels and inhibit the development of glioma and leukemia." (PMID 37996930, 2023). "R-2HG inhibits FTO protein activity, resulting in elevated global mRNA m6A levels in R-2HG-sensitive leukemia cells." (PMID 37007161, 2023). "FTO inhibition significantly decreased leukaemia stem cell self-renewal by abolishing the increase in LILRB4 expression and sensitized human AML cells to T-cell cytotoxicity." (PMID 36859310, 2023). "FTO is a potential target in leukemia, the depletion of which dramatically impaired leukemia stem cell, initiated cell-renewal ability, and suppressed immune evasion." (PMID 37028765, 2023). "In vivo analysis further confirmed that targeting FTO/m6A/LILRB4 overcomes immune evasion in leukaemia." (PMID 36859310, 2023).